CD44 (CD44 molecule (IN blood group))
Diseases named in the same sentence as CD44 in open-access papers (continued):
Sharing a sentence is not in itself a finding about the gene and the disease.
cancer (continued). "Because different sub-populations of CD44/CD24 are used to isolate cancer stem cells in different cancer types, we FACS-sorted all four sub-populations and implanted them." (PMID 26449187, 2015). "CSCs have been identified in many solid tumors, including breast, lung, colon, prostate, ovary, brain cancer, and sarcoma; in H&N cancer, the existence of CSCs was first assessed using CD44 as a stem cell marker." (PMID 25428916, 2015). "Studies have shown that binding of HA to CD44 in cancer cells activates survival pathways resulting in cancer cell survival." (PMID 25870596, 2015). "As shown here a large fraction of MiaPaCa-2 cells are ALDH positive and display some characters of stem-like cancer or cancer initiating cells such as the expression of the cancer stem-cell CD44 marker, of embryonic transcription factors Nanog and Oct4." (PMID 25821841, 2015). "Our work, together with the work of Misra and colleagues, demonstrates that P-gp expression in cancer cells is tightly controlled by CD44." (PMID 26299618, 2015). "The differential uptake efficiency of HA-coated nanoparticles observed between normal and cancer cells is potentially induced by activated CD44." (PMID 25909172, 2015). "HA is a negatively-charged polysaccharide with a relevant role in cancer since its receptors (CD44, RHAMN) are overexpressed on the surface of a broad variety of cancer cells." (PMID 25888948, 2015). "The cell surface glycoprotein CD44 is expressed in cancer cells and has been used as a therapeutic target in preclinical studies." (PMID 25909172, 2015). "Several recent studies have also focused on the function of CD44 isoforms in various types of cancer upon the addition of HA." (PMID 25954275, 2015). "Many malignancies express CD44, thus using HA as a homing missile for cancer therapeutics is a logical step." (PMID 26539408, 2015). "CD44 (hyaluronic acid receptor) is a cancer stem cell marker and a potential pluripotency marker involved in cell–matrix interaction, homing, adhesion, matrix assembly, and apoptosis resistance." (PMID 26297012, 2015). "Since the discovery that HA receptor, CD44 is a stem cell marker, targeting of CD44 for anti-cancer therapy has been attempted using DNA vaccines, anti-CD44 monoclonal antibodies, and nanoparticle-mediated delivery of CD44siRNAs." (PMID 25954275, 2015). "Coincidentally, cancer stem cells marker CD44 has been reported to represent a low level of stemness in induced pluripotent stem (iPS) cells." (PMID 26540347, 2015). "Nowadays, CD44 is an established marker of cancer stem populations in breast, prostate, pancreas, ovarian and colorectal cancers." (PMID 25629807, 2015). "In this report, we show that the NGF/TrkA axis engages CD44 as a co-receptor to strengthen cancer cell invasion and growth." (PMID 25840418, 2015). "Continued discovery of novel roles for CD44 in cancer development will help expand the mounting potential of CD44 as a prime therapeutic target." (PMID 25954275, 2015). "Our new findings expand the current understanding of the regulation of cancer drug resistance by CD44, demonstrating the CD44-mediated inhibition of P-gp ubiquitination." (PMID 26299618, 2015). "A considerable number of studies indicate that CD44 isoforms correlate with bad prognosis in patients with most human cancers except in neuroblastomas and prostate cancer." (PMID 26448753, 2015). "The percentages of cancer stem cell-like CD44+/ESA+ cells increased markedly by 5-10-fold after X-ray irradiation, whereas the proportion of these cells only doubled or decreased after carbon ion irradiation." (PMID 25849939, 2015). "Conversely as CD44 is a marker for chronic autoimmune disease and plays an important role in cancer metastasis inhibiting the CD44/HA interaction though redox changes offers a mechanism of regulating such processes." (PMID 26379032, 2015).
cancer (continued). "Recent studies have identified several cancer stem-cell surface markers including CD133, CD44 and EpCAM, although global markers for CSCs in different human cancers are difficult to establish." (PMID 26506419, 2015). "One approach has been to chemically modify HA to allow attachment of carboxyl-containing drugs, and an HA-Paclitaxel prodrug bioconjugate has been prepared that showed selective toxicity against cancer cells overexpressing CD44." (PMID 26448751, 2015). "While several excellent reviews have been focused on CD44–HA signaling and its implications in cancer, this review focuses on both HA-independent (mainly) and HA-dependent functions of CD44 in the pathophysiology of various diseases." (PMID 25954275, 2015). "CD44 is a downstream target of Wnt signaling and is considered one of the most important markers of cancer stem cells (CSCs)." (PMID 26429859, 2015). "Percentages of CD44+ cancer cells in 10 randomly chosen fields of each slide were scored as: 0 points for 0–5 %, 1 point for 5–25 %, 2 for 25–75 % and 3 points for >75 % cells." (PMID 25129125, 2015). "One caveat of using HA as a tag to target chemotherapy to CD44+ cancer cells is the abundant expression of the HA receptor HARE/Stab2 in the liver, thus special attention to liver toxicity is essential in such studies." (PMID 26539408, 2015). "Since miR-34a suppresses many oncogenes and cancer stem cell markers including CD44, CDK4, CDK6, c-Met, Notch-1, Notch-2, SIRT1 and DLL1 as its target genes, miR-34a plays important roles in cancer stem cells." (PMID 26580663, 2015). "CD44 affects carcinogenesis of many cancers through several mechanisms, notably cell migration and metastasis initiation." (PMID 25129125, 2015). "CD44 is prevalently upregulated at various stages of the cancer evolution, and the protein also mediates adhesion between stroma cells and bone marrow progenitor cells." (PMID 25978366, 2015). "It is often involved in tumorigenic processes influencing proliferation, migration and survival, as well as the adhesive properties of cancer cells via CD44 and integrin signaling pathways." (PMID 25616494, 2015). "Although CD44 has been identified as a cancer stem-like cell biomarker in NPC cell lines, its potential role in tumorigenesis has not been proven in vivo." (PMID 26202311, 2015). "In this study, we demonstrate that two distinct CD44 states exist and that these states differ in human breast cancerous and normal tissue: active CD44 is found on cancer cells and inactive CD44 is found on normal cells." (PMID 25909172, 2015). "Further 85.3 +/− 10.4 % of these cells also expressed CD44 (a cancer stem cell related surface marker,)." (PMID 25821841, 2015). "Another surface marker protein used extensively to identify cancer stem cells is CD44, a transmembrane glycoprotein." (PMID 26449187, 2015). "The results showed that stemness genes (Nanog and Oct-4), multiple drug-resistant transporter gene (ABCG2) and surface antigens associated with cancer stem cells (CD24, CD44 and CD133) were upregulated in ZIPK-transfected cells compared with control cells." (PMID 25831050, 2015). "CD44 is expressed in both normal and cancer stem cells (CSCs) and serves as an important stem cell marker." (PMID 26448762, 2015). "Our present work provides further insight into the regulation of P-gp expression by CD44 which is needed to more effectively design the next generation of compounds that will both overcome multidrug resistance in cancer cells and be less toxic to normal cells." (PMID 26299618, 2015). "Our results indicate that the CD44 expression pattern differed between normal cells and cancer cells." (PMID 25909172, 2015). "Recently, combination of chemotherapeutic drugs with HA NPs for selective targeting of CD44-overexpressed cancer cells has received increasing attention to improve specificity of the drug and alleviate side effects." (PMID 25888948, 2015).
cancer (continued). "The percentage changes of cancer stem like CD44+/CD24- cells in MDA-MB-231 cells and ESA+/CD24- cells in MDA-MB-453 cells 72 h or 96 h after carbon ion beam, X-ray alone or in combination with 25 μM of CDDP were investigated by FACS analysis." (PMID 26338199, 2015). "We found that the percentages of cancer stem-like CD44+/CD24- cells in MDA-MB-231 cells were dose-dependently increased after 72 h X-ray irradiation, whereas no such clear dose–response was observed after carbon ion beam." (PMID 26338199, 2015). "A challenging area of research would be to define what cellular functions are associated with the various CD44 isoforms that are overexpressed in various cancers before a CD44-based therapy can be undertaken." (PMID 25999946, 2015). "The role played by CD44 in the interaction between cells and the bioconjugate was assessed in a competition assay where target cancer cell lines were incubated with an anti-CD44 blocking mAb, and then with BODIPY-labeled ONCOFID-S." (PMID 26097871, 2015). "MCF-7/ADR-1024 and MCF-7/ADR express high levels of drug transporter ABCB1 gene, detoxifying gene GST-π, basal-like gene N-cadherin and cancer stem cell surface marker CD44 gene." (PMID 25635866, 2015). "We demonstrate that the bioconjugates were (i) properly constructed, (ii) selectively internalized in CD44 over expressing cancer cells, and (iii) able to induce apoptosis." (PMID 27182458, 2015). "Recent studies have also implicated some cancer stem cell (CSC) markers such as CD133, ALDH1 and CD44 in VM formation." (PMID 26460958, 2015). "Sarcomatoid areas of cancer sphere xenografts were strongly positive for the mesenchymal marker CD44, in agreement with the literature." (PMID 25011053, 2015). "CD44 can be detected in the process of lymphocyte activation, recycling and homing, cancer development and metastasis." (PMID 26540347, 2015). "In several types of tumors, CD44 together with other cell surface markers characterizes cancer stem cell populations." (PMID 26569327, 2015). "Consistent with previous reports that EMT promotes stemness, the expression of a well-known cancer stem cell marker CD44 decreased upon Ovol2-induced transition to E and increased upon Zeb1/Snail-induced transition to M." (PMID 26554584, 2015). "We then examined the influence of EGF on MMP9 transcription as well as on the transcription of additional MMPs (MMP-1, MMP-2, MMP-3, MMP-7, MMP-10, MMP-13, MMP14, MMP15) and of CD44, a cell adhesion glycoprotein implicated in EMT and cancer metastasis." (PMID 26084289, 2015). "CD44 as one of the most putative stem cell markers plays a key role in many cellular processes, including cancer cell growth and migration." (PMID 26010608, 2015). "The MCF-7 cells have a very small population of cancer stem cells with an average of 0.38% for CD44+/CD24− cells." (PMID 25885813, 2015). "CD44 is of functional importance for maintaining the stem cell-like phenotype and for supporting cancer cell expansion." (PMID 26418878, 2015). "Fluorescence imaging confirmed selective internalization of the Cyt c-HA construct by CD44-positive cancer cell lines." (PMID 27182458, 2015). "This behavior can be understood under the assumption that each cancer cell line has very particular apoptotic and anti-apoptotic mechanisms and overexpression levels of CD44." (PMID 27182458, 2015). "A6 has demonstrated clinical safety and efficacy, and by targeting CD44-resistant cells to prevent metastases and recurrence, has the possibility of creating a new paradigm for cancer treatment." (PMID 25870596, 2015). "The observation that ALDH+ve/CD44+ve cancer stem cells showed low levels of miR-145 reinforced its importance as an effective approach to target the stem cell population in cancer." (PMID 26425114, 2015). "The pathways regulated by CD44 in these fibroblasts have yet to be determined, but the studies from Ni and Kinugasa illustrate the complex nature of CD44 signaling in cancer." (PMID 25954275, 2015).
cancer (continued). "At present, the most effective strategy for CD44 targeted anti-cancer therapeutics is anti-CD44 antibodies." (PMID 25909172, 2015). "In the present study, FACS analyses showed that the proportion of cancer stem-like CD44+/ESA+ cells was more highly enriched after X-rays compared to carbon ion irradiation." (PMID 25849939, 2015). "The expression of the cancer stem-like cell marker CD44 and the novel HNSCC stem-like cell marker CD44v6 did not change considerably with increasing drug concentrations." (PMID 26452257, 2015). "The majority of malignant tumors contain elevated levels of both HA and CD44, and it has been demonstrated that HA-activated CD44 promotes the proliferation, invasion, metastasis and stemness of cancer cells." (PMID 26005723, 2015). "Our findings suggest that it will be productive to evaluate the CD26/CD44/CD133/CXCR4 status of refractory cancer cells in future studies of CRC." (PMID 26552750, 2015). "DU145R80 show a cancer stem cell (CSC)-like signature with a high expression of CSC markers including CD44, CD133, NANOG, Snail, Oct4 and ALDH7A1 and CSC-related genes as STAT3." (PMID 26312765, 2015). "This task can be accomplished by exploiting cancer-specific receptors and the related ligands, CD44 and hyaluronic acid (HA) representing a notable example." (PMID 26097871, 2015). "The interaction between CD44 and hyaluronan is known to promote both transformation and metastasis of cancer cells." (PMID 26588071, 2015). "In solid tumors (like the colon), these subpopulations of cells, which express cell surface markers like CD44, are termed cancer stem-like cells." (PMID 25879211, 2015). "Two CD44-positive cancer cell lines, HeLa and A549 cells, and two CD44-negative normal cell lines, Huvec and NIH-3T3 cells, were incubated with the samples to evaluate cellular internalization and cytotoxicity." (PMID 27182458, 2015). "After 6 hours of platelet addition to these cancer cells we observed an increase in TF and CD44, with a decrease in E-Cadherin in all patients." (PMID 25886038, 2015). "Alternative splicing of CD44 was confirmed using RT-PCR, which revealed that the CD44ν3-10 isoform was only expressed in patients with cancer recurrence." (PMID 26572077, 2015). "MEK but not mTOR inhibition in vitro induced cytotoxicity, reduced inflammatory cytokine secretion and CD44 expression and reduced migratory capacity in MOC1 and MOC2 cells, consistent with the Ras-driver mutations shared by these carcinomas." (PMID 26506415, 2015). "Whereas the standard isoform of CD44 is mainly expressed in hematopoietic and normal epithelial cells, the CD44 isoforms (CD44v), which contain insertions in the extracellular region proximal to membrane, are highly expressed in epithelial-type carcinomas." (PMID 26064420, 2015). "It is generally accepted that ALDH activity and CD44 expression are reliable markers for CSC identification in carcinomas from the head and neck areas." (PMID 25428916, 2015). "For example, in the A431 human epithelial carcinoma cell line, miR-328 overexpression resulted in reduced cell adhesion, aggregation, and capillary formation by silencing CD44." (PMID 25605016, 2015). "Since CD44 was identified as the first integral HA binding “receptor”, HA-mediated CD44 signaling has received a great deal of attention in cancer field." (PMID 24606718, 2014). "In combination with other surface markers, CD44 can also be used to discriminate between a variety of cancer subsets." (PMID 24765173, 2014). "Blood group antigens are present on key receptors, which differ according to the cancer type, and control cell proliferation, resistance to apoptosis and adhesion, such as receptors for integrins, cadherins, epidermal growth factor and CD44." (PMID 24516588, 2014).
cancer (continued). "10AT-Her2 cells display a CD44+/CD24-/low phenotype with high levels of the cancer stem/progenitor cell marker proteins nucleostemin, and active aldehyde dehydrogenase-1 (ALDH-1)." (PMID 25209720, 2014). "It has been proposed that it is not the mutation of CD44, but the factors promoting carcinogenesis, that control the patterns of the misregulated CD44 in most cancers." (PMID 24699672, 2014). "CD44 is a glycoprotein that mediates the interaction of cancer cells to E-selectin expressed on endothelial cells." (PMID 25343626, 2014). "Higher phosphorylation and consequent inactivation of Rb was observed in the CD44+/CD24−/Low subpopulation compared to bulk SUM149PT cancer cells." (PMID 24970653, 2014). "Despite intense research focused on CD44 as a target for cancer therapies, the mechanism by which the protein is up-regulated in cancer and TICs is not well understood." (PMID 25184276, 2014). "Because of overexpression of CD44 receptors by cancer cells, interfering in CD44-HA interaction by targeting drugs at CD44 is an effective strategy to treat cancers." (PMID 24868467, 2014). "The IRS of the cancer cells with membranous CD44 expression ranged from 0 to 12 (median 3.4), with 16/28 (57.1%) cases considered positive." (PMID 25240521, 2014). "BENSpm and Pd-BENSpm treatment reduced the CD44+CD24− putative cancer stem cell population, evaluated by flow cytometry." (PMID 24363201, 2014). "CD44 is expressed as multiple isoforms in normal and cancer tissues throughout the body due to alternative splicing events." (PMID 25309501, 2014). "CD44 has also been recently recognized as a cancer stem cell surface marker in several cancer types, and CD44 expression in cancer cells promoted bone metastasis by enhancing tumorigenicity, cell migration and invasion, and HA production." (PMID 25304388, 2014). "DDX3X expression was associated with upregulation of Sox2 and increase of cancer cells exhibiting CSC-like phenotypes, such as anchorage-independent proliferation, strong expression of CD44, and aldehyde dehydrogenase (ALDH)." (PMID 25343452, 2014). "Recently CD44 has been recognized as a marker of putative cancer stem cells, in particular of squamous phenotype; CD44 high expression plays a crucial key role in initiation, malignant transformation, and EMT-like program." (PMID 24959179, 2014). "The prognostic value of CD44 for patients with cancer has been reported in various solid tumors, including colon, lung, and breast cancer." (PMID 25112408, 2014). "Decreased expression of THBS1 and CD44, a cancer stem cell marker, in TPC1 and BCPAP cells with Y15 that were detected by microarray were also validated by Western blotting." (PMID 25277206, 2014). "In these starvation experiments, designed to increase the population of cancer stem-like cells, we were able to enrich the proportion of CD44-positive cells by culturing in low serum containing cell medium with EGF and bFGF." (PMID 24122205, 2014). "The ALDHlow fractions also co-expressed CD44 although at much lower frequencies in H28 (1.8%), H2052 (2.0%) and Meso4 (1.1%) relative to all cancer cells." (PMID 24884875, 2014). "Many researchers have reported that high expression of these markers indicates bad clinical features and poor prognosis, and CD44 was one of the most reported cancer stem cells markers." (PMID 25112408, 2014). "Cancer cell adhesion to endothelial cells is an important step of metastasis and is known to be regulated by CD44 in many cancer cells." (PMID 24823486, 2014). "The number of CD44+ cells was reduced markedly (to 9%) by treatment with sodium butyrate (NaBt), which is a well know inducer of differentiation in cancer cell lines including Caco2." (PMID 24960044, 2014). "High CD44 levels are a marker for tumor initiating and chemotherapeutic-resistant cells in many cancers, including breast." (PMID 24990559, 2014).